EGFR (epidermal growth factor receptor)
Diseases named in the same sentence as EGFR in open-access papers (continued):
Sharing a sentence is not in itself a finding about the gene and the disease.
cancer (continued). "Both Clinicopathology features that gender and smoking history, degree of invasion, and morphology features like cancer density and the vacuole sign, were independent predictors for the EGFR mutant phenotype." (PMID 35186727, 2022). "Aberrant expression of EGFR is observed in up to 60% of GBMs and leads to unrestrained cell growth and replication, as well as an increase in the cancer's aggressive potential." (PMID 35145836, 2022). "The signal of AREG, which is an EGFR ligand, has been observed to stimulate cancer cell invasion and activate the EGFR pathway to induce osteoclastogenesis." (PMID 35158999, 2022). "Other study also found by CRISPR-Cas9 screening that targeting EGFR sensitized cancer cells to T-cell cytotoxicity." (PMID 35372044, 2022). "EGFR was the first family member shown to be overexpressed in cancers and it is therefore a primary target for anti-cancer therapies." (PMID 35232398, 2022). "Tyrosine kinase inhibitors (TKIs) targeting the receptor tyrosine kinase (RTK) EGFR are effective treatments in cancer patients with EGFRm." (PMID 35360705, 2022). "Epidermal growth factor receptor (EGFR), another protein specifically overexpressed in tumors, is closely associated with cancer progression." (PMID 35757760, 2022). "Iodo silanes are presented as a superior alternative in a case study describing the synthesis of MIPs against epitopes of a common cancer biomarker, epidermal growth factor receptor (EGFR)." (PMID 35458345, 2022). "Gefitinib induces apoptosis by inhibiting EGFR and exerts anti-cancer effects by inhibiting angiogenesis through suppression of vascular endothelial growth factor production." (PMID 35892692, 2022). "The role of EGFR activation has been well studied in cancer angiogenesis and proliferation of cancer cells, and EGFR antagonists and/or blocking antibodies are used to treat, or are being studied as treatments for, certain types of cancers." (PMID 35674115, 2022). "Through database analyses, we identified EGFR/HER2 signaling to be essential in human cancers with high TAZ activity." (PMID 35439973, 2022). "As expected, EGFR increased the free uptake of B-ASO which is characteristic for cancer cells overexpressing EGFR." (PMID 36499115, 2022). "To define the alteration of sensitivity of cancer cells to one of the EGFR inhibitors, gefitinib, in response to the methionine depletion, we started with the assessment of EGFR mRNA level in H1299 and SK-BR-3 cells treated with MGL S3 and MGL tetani for 48 h." (PMID 36361596, 2022). "However, both have been detected in cancer samples.Interestingly, molecular dynamics (MD) simulations suggest that theL658Q mutation located in the hydrophobic transmembrane region formsintermolecular hydrogen bonds, thereby promoting EGFR dimerizationand activation." (PMID 36148499, 2022). "An antibody known as cetuximab (Erbitux) targets the EGFR cell protein, which is present in healthy skin cells (as well as some types of cancer cells)." (PMID 36341340, 2022). "We found that the expression level of EGFR in cancer tissues was significantly higher than that in paracanerous tissues." (PMID 36551506, 2022). "HDAC3 enhanced the sensitivity of anti-cancer drug-resistant melanoma cells to anti-cancer drugs by negatively regulating EGFR signaling and CAGE expression." (PMID 35682560, 2022). "We also determined that N-glycosylated CGA bound to EGFR and activated EGFR signaling, which provided a survival advantage to cancer cells during chemotherapy." (PMID 35289315, 2022). "Multiple targeted therapy drugs have been applied in the treatment of diverse cancers, such as cetuximab and panitumumab targeting the epidermal growth factor receptor (EGFR), and trastuzumab targeting HER-2." (PMID 36100944, 2022). "A new class of EGFR PROTACs based on pomalidomide was developed, synthesised, and tested for their cytotoxic activity against a panel of human cancer cells." (PMID 35470756, 2022).
cancer (continued). "More interestingly, EGFR can enhance the CD44–mediated cancer cells aggregation and CD44 can stabilize EGFR in turn." (PMID 36059616, 2022). "In fact, the cholesterol levels in the lipid raft are important for regulating EGFR activity and cancer cells are more sensitive to EGFR-targeted therapy upon cholesterol depletion from lipid rafts due to increased phosphorylation levels." (PMID 36497413, 2022). "This system allowed to test EGFR, HER2, CA125, FRa, CD24, EpCAM, CD9, and CD63 in OC-EVs with a diagnostic power in early cancer diagnosis." (PMID 35884464, 2022). "MET amplification is an important mechanism by which cancers develop resistance to epidermal growth factor receptor (EGFR) inhibitors and FGFRis, and a high MET GCN has been detected in 1–11% of NSCLCs." (PMID 35402233, 2022). "These drugs are becoming less effective in EGFR targeted cancer treatment and developing resistance to cancer cell eradication, which sometimes necessitates stopping treatment due to the side effects." (PMID 36457709, 2022). "Insufficient suppression of the EGFR/KRAS network induced insensitivity to MIR143#12 in EGFR or KRAS mutant cancer cells." (PMID 36189421, 2022). "The compounds were investigated for their ability to inhibit EGFR, their effect on cancer cell cycle and their ability to induce apoptosis." (PMID 36146940, 2022). "These fishing rods bound (among others) to EGFR protein present in protein lysates from EGFR-overexpressing A431 cancer cells." (PMID 36499115, 2022). "Both the insulin-like growth factor 1 receptor (IGF-1R) and epidermal growth factor receptor (EGFR) were implicated in the development, progression, metastasis, and chemotherapy resistance of a variety of cancers." (PMID 36142299, 2022). "We validate that these phenotypes are driven by EGFR signaling with pharmacological, biochemical, and classical cancer biology assays." (PMID 35157848, 2022). "The ERBB/EGFR signalling pathway is dysregulated in numerous cancers, especially of the lung, breast and ovary." (PMID 35971826, 2022). "The human epidermal growth factor receptor (HER) family is a tyrosine kinase receptor consisting of EGFR, HER2, ErbB3, and ErbB4, which is associated with the formation and progression of malignant tumors." (PMID 35804953, 2022). "In order to understand the pharmacokinetics of gefitinib and to develop a tool to non-invasively determine the EGFR status of cancer cells in vivo, [18F]- and [O-methyl-11C]gefitinib were developed." (PMID 35455447, 2022). "CD44v6 is highly expressed in many cancers, and acts as co−receptor for at least three receptor tyrosine kinases (c−Met, EGFR, and VEGFR−2), which contribute to the oncogenic functions of CD44v6." (PMID 35628345, 2022). "A recently developed dual inhibitor of visfatin and EGFR has shown excellent antiproliferative activities in various cancer cell lines, including H1975 NSCLC cells harboring the EGFRL858R/T790M mutation." (PMID 36429891, 2022). "Trispecific mAbs against TfR, EGFR, and, specifically, highly expressed cytosol molecules that are essential for cancer cells are the most potent targets to elicit anti-cancer activity in cancer cells." (PMID 35884906, 2022). "The R9VH36 have previously reported that they were able to decrease the viability of the EGFR-driven cancer cell, A549, in a nanomolar range which is." (PMID 35578244, 2022). "PGRMC1 dimerizes via heme and the dimer interacts with cytochrome P450 and epidermal growth factor receptor (EGFR) in order to increase cancer cell growth and resistance to chemotherapy." (PMID 36008941, 2022). "LPA was clarified to transactivate the epidermal growth factor receptor (EGFR) in a classic autocrine manner in some cancer cells." (PMID 36601056, 2022). "Considering that many small molecules applied as cancer therapeutic agents are hydrophobic, which limits their delivery, EGFR-targeted nanoparticles can have a dual function for increasing the drug’s solubility and stimulating tumor-targeting properties." (PMID 36559202, 2022).
cancer (continued). "And nuclear EGFR always interacts and phosphorylates several proteins to contributes to cancer progression." (PMID 35013116, 2022). "In light of the prominent and multi-faceted roles of EGFR, therapeutic strategies taking advantage of EGFR signaling have been proposed for cancer treatment." (PMID 36551308, 2022). "Tyrosine kinase inhibitor (TKI) drugs have revolutionised the treatment of many cancers and TKIs such as gefitinib, erlotinib, and lapatinib that inhibit the EGFR are effective agents in the treatment of certain cancers." (PMID 35908023, 2022). "The EGFR gene promotes the growth of various solid tumors and is elevated in multiple types of cancer." (PMID 36144596, 2022). "KEGG and GO enrichment analyses showed the potential impact of the “PI3K-Akt signaling pathway,” “ErbB signaling pathway,” “Focal adhesion,” and “Proteoglycans in cancer” or “EGFR tyrosine kinase inhibitor resistance” of cancers." (PMID 35601500, 2022). "Following radiation, the activation of EGFR has been reported, leading to downstream signaling that contributes to cancer cell survival." (PMID 36139779, 2022). "Platelets of high D-dimer plasma had higher adherence capacity to cancer cells, and induced EGFR and Akt activation as well as EMT through Src activation." (PMID 35756605, 2022). "Previous approaches have used antibodies or ligands with the highest affinity to a cancer antigen target receptor for IT development, including EGFR-targeted ITs." (PMID 36555466, 2022). "The targeted drugs currently studied in combination with PARP for the treatment of cancer mainly include anti-angiogenic drugs (such as bevacizumab) and EGFR-targeted drugs (such as cetuximab)." (PMID 36091750, 2022). "In summary, our research identified that EGFR L858R neoantigen had the potential to generate cancer vaccines in NSCLC patients with HLA A*33:03 and revealed the possible underlying immunological features between EGFR mutant subtypes." (PMID 36505399, 2022). "M3-EGFR demonstrated the ability to bind and internalize specifically and provide the anticipated intracellular nuclear import of three different EGFR-targeted modular nanotransporters designed for specific anti-cancer drug delivery." (PMID 36432639, 2022). "Accordingly, mutations in MUC16 (CA125) were selected for in EGFR-mut and KRAS-mut cancers while only mutations in MUC17 were selected in NEK." (PMID 36612014, 2022). "Inhibitors of EGFR were among the first targeted drugs for cancer and currently constitute the standard of care for lung and CRC patients." (PMID 35053365, 2022). "Encouragingly, the UniCAR-T-EGFR cells also show activity against cancer cells expressing low levels of EGFR." (PMID 36185288, 2022). "EVs with either an epidermal growth factor receptor (EGFR)-targeting peptide or anti-EGFR nanobody improved their accumulation in EGFR+ cancer cells." (PMID 35336027, 2022). "Because long-term use is easy to leads to anti-EGFR treatment resistance, cetuximab resistance is the main clinical drug resistance problem in the treatment of EGFR overexpression cancer." (PMID 35963853, 2022). "The epidermal growth factor receptor (EGFR) is one of the most frequently examined cancer biomarkers in fluorescent imaging, as it is frequently altered in various human cancers." (PMID 35701793, 2022). "Herein, in the EAC cell line, a well-established cancer cell line with overexpression of EGFR is known to be involved in oxidative stress and cancer progression." (PMID 35421091, 2022). "A similar process was also observed with EGFR CAR T cells during their contact with carcinoma cells from several cell lines." (PMID 35681548, 2022).
cancer (continued). "Squamous carcinoma cancer cells can respond to matrix stiffening, by increasing EGFR expression, thus sensitizing carcinoma cells to EGFR phosphorylation, resulting in increased actomyosin contractility and collective invasion." (PMID 35727208, 2022). "We found EGFR/MET were mainly expressed in HCC cells of carcinoma tissue, which differed from some RTKs for clinical targets expressed mainly in peritumor tissue such as the PDGFR family." (PMID 35428350, 2022). "Beyond genomic/epigenetic alterations of oncogenes and/or tumor suppressors, the epidermal growth factor receptor (EGFR) ligand EREG can function as a bona fide biomarker of therapeutic sensitivity for many EGFR-driven carcinomas." (PMID 36202915, 2022). "For instance, treatment of PDA cells with recombinant TNF-α increased EGFR expression from carcinoma cells, while in another study recombinant TNF-α promoted the growth of Panc02 tumors in mice but inhibited KPC cell growth." (PMID 36256464, 2022). "It has been demonstrated that epidermal growth factor receptor (EGFR) signaling involves multiple biological possession of carcinoma, including cell proliferation, migration, and survival." (PMID 36147736, 2022). "The results confirmed a significant increase of EGFR values, mostly in poorly differentiated carcinomas compared with moderately and well differentiated ones." (PMID 35406495, 2022). "Under low ICAM-1 expression and despite efficient target antigen expression, EGFR CAR T cells were unable to form productive conjugates with carcinoma cells." (PMID 35681548, 2022). "EGFR is overexpressed in many human carcinomas and is also involved in developing resistance to chemotherapy." (PMID 35409325, 2022). "EGFR blocking antibodies have been successfully implemented for the treatment of various types of carcinoma, including breast cancer, renal cell carcinoma, non‐small cell lung cancer (NSCLC) and others." (PMID 35908284, 2022). "Recently, SNX3 was also shown to bind with EGFR using biotin proximal labelling approach, and SNX5 immunoprecipitated with EGFR in Huh7—a hepatocyte-derived carcinoma cell line." (PMID 36359754, 2022). "EGFR variants proved to be a conventional predictive marker for selecting first-line EGFR-TKI treatment for NSCLC patients with high-grade carcinomas." (PMID 35892510, 2022). "All HPV16-positive LDS carcinomas in the present study were EGFR wild-type, supporting the mutual exclusivity between high-risk HPV positivity and EGFR mutation observed in the SCC of the neighboring sinonasal cavities." (PMID 35626161, 2022). "The adenocarcinoma cell lines AU565 and SK-OV-3 expressed high levels of HER2 and EGFR, whereas the carcinoma cell line A431 expressed low levels of HER2 and high levels of EGFR." (PMID 36713381, 2022). "The activity of the conjugates was analyzed in primary cultures of human head and neck tumor cells with high-level expression of EGFR, and in human carcinomas grown as xenografts in mice." (PMID 36232384, 2022). "Our results provide new insights into architectures, dynamics and interactions of EGFR molecules overexpressed in carcinoma cells." (PMID 35612280, 2022). "CD44 is an important marker of CSC’s in carcinomas, and it plays a role in the mediation of resistance to drug therapy, including anti-EGFR inhibitors." (PMID 35011716, 2022). "Sin embargo, un estudio reportó que la capacidad de invasión estaba inversamente correlacionada con la expresión del EGFR en pacientes con carcinoma oral de células escamosas." (PMID 38389655, 2022). "On the surface of carcinoma cells, EGFR forms a complex with CD147, which is also upregulated: this leads to the phosphorylation of AKT and MAPK, which is followed by the formation of invadopodia." (PMID 35955471, 2022). "This seems to be a common phenomenon that is detectable in cell lines of different carcinoma entities and is communicated as being associated with epithelial to mesenchymal transition (EMT) and the EGFR pathway." (PMID 36230826, 2022).
cancer (continued). "Uptake of HB-Au-NPs was observed only in cancer cells that overexpressed EGFR and ErbB2 using photoacoustic microscopy." (PMID 34832857, 2021). "In conclusion, malignant cancer cells hijack alternate pathways to survive anti-EGFR/HER2 therapy and grow and migrate or stay dormant." (PMID 34074257, 2021). "Dysregulation of EGFR protein stability is shown to critically contribute to abnormal EGFR signaling and cancer development." (PMID 34635651, 2021). "Although this study only focused on EGFR mutations and therapies in NSCLC, future studies can explore a similar approach for EGFR mutant cancers or other GFs driving oncogenic transformations to improve the current therapies." (PMID 33854965, 2021). "In conclusion, these results demonstrate the apoptotic effects of DPT on HCC827GR cells and signify the potential of DPT to serve as an adjuvant anti-cancer drug by simultaneously inhibiting EGFR and MET." (PMID 33746190, 2021). "EGFR-Src-STAT3 signaling is also considered as an important pathway in tumorigenesis in various cancer types." (PMID 33925065, 2021). "Epidermal growth factor receptor (EGFR) is a target for cancer therapy as it is overexpressed in a wide variety of cancers." (PMID 33711962, 2021). "EGFR inhibition has been shown to sensitize cancer cells to radiation therapy through potentiating, for instance, cell cycle arrest and apoptosis." (PMID 34298879, 2021). "Cinobufagin blocked EGFR phosphorylation and its downstream signaling, which additionally induced apoptosis and cytotoxicity in EGFR amplified cancer cells." (PMID 34925034, 2021). "Four bio-orthogonal click probes modified with trans-cyclooctene (TCO) were designed to enable the specific targeting of three cancer proteins (EGFR, EpCAM and MUC1) and one generic EV marker (CD63)." (PMID 34855021, 2021). "The mutational status of RAS correlates with the clinicopathological features of patients, such as mucinous type and poor differentiation, as well as response to anti-EGFR therapies in certain types of human cancers." (PMID 34301278, 2021). "This chimeric EGF-ETA toxin targets and inhibits EGFR-positive cancer cells, potentially allowing it to be used to target EGFR-positive tumors that are resistant to monoclonal antibodies." (PMID 34884780, 2021). "The common exosome markers, including CD63, CD81, and CD9 and the cancer marker EGFR, are detected in A549 cell-derived exosomes with a Western Blot." (PMID 34769444, 2021). "While a relatively limited number of known oncogenes (e.g., RAS, MYC, PIK3CA, EGFR, BCR-ABL) seem to underlie a large percentage of cancers, a variety of new genes have emerged as low-frequency cancer drivers." (PMID 34504101, 2021). "EGFR inhibitors inhibit cancer cell growth by binding to a specific part of EGFR and blocking signaling." (PMID 33567635, 2021). "microRNAs (miRs) have recently emerged as factors involved in EGFR-mediated functions in cancer cells." (PMID 33952719, 2021). "The precedent of a targeted cancer therapeutic with conditional approval is the anti-epidermal growth factor receptor (EGFR) antibody cetuximab (Erbitux®)." (PMID 33920536, 2021). "Several studies have shown that changes in the level of expression of proteins regulating EGFR trafficking affect cancer cell sensitivity to targeted therapies." (PMID 34831480, 2021). "EGFR, a member of receptor tyrosine kinases (RTKs), is essential to the pathological process in various cancers via activation of PI3K/Akt signaling pathway." (PMID 34461927, 2021). "Sialylation is another important abnormal glycan modification found in the vast majority of cancers, which leads to the hyperactivation of the receptor tyrosine kinases (RTKs), like epidermal growth factor receptor (EGFR), MET, and RON." (PMID 34745942, 2021).